INS (insulin)
Diseases named in the same sentence as INS in open-access papers (continued):
Sharing a sentence is not in itself a finding about the gene and the disease.
Alzheimer disease (continued). "However, DPP-4is reportedly increases the risk of Alzheimer’s disease by aggravating tau phosphorylation and insulin resistance in the hippocampus and primary neurons of OLEF (Otsuka Long-Evans Tokushima Fatty) rats." (PMID 30597861, 2018). "The impairments in glucose metabolism, insulin signalling, insulin sensitivity and lipid metabolism, as well as increases in inflammation and oxidative stress in central nerve and peripheral system, contribute to the risk of Alzheimer’s disease (AD)." (PMID 30250013, 2018). "The present data have far-reaching clinical implications and raise the hypothesis that pathophysiological tau loss-of-function favors brain insulin resistance, which is instrumental for cognitive and metabolic impairments in Alzheimer’s disease patients." (PMID 28652303, 2017). "Disrupted insulin signaling has been associated with the development of Alzheimer’s disease." (PMID 28162091, 2017). "Indeed, Alzheimers Disease (AD) is closely associated with impaired insulin signalling and glucose metabolism and is often referred to as “type 3 diabetes”." (PMID 27467571, 2016). "Insulin might also affect memory through its inhibition of insulin degrading enzyme that in turn leads to a failure to degrade amyloid-β, a hallmark of Alzheimer’s disease." (PMID 25798199, 2015). "An inadequate glucose metabolism in the brain resulting from insulin resistance, the reduced ability of insulin to stimulate glucose utilization, is at the center of new therapeutic avenues to treat the most common cause of dementia worldwide, that is, Alzheimer's disease (AD)." (PMID 25815110, 2015). "In addition, the association between glucose, insulin and lipid metabolism and the underlying neurobiological changes observed in patients with Alzheimer’s disease are being established." (PMID 26193295, 2015). "The epidemiological data suggest that brain insulin resistance flanks both cognitive decline and progressive neuroinflammation in neurodegenerative diseases; in particular, type II diabetes represent a risk factor to develop Alzheimer’s disease." (PMID 25889938, 2015). "Studies in humans and animal models show that neuronal insulin resistance increases the risk of developing Alzheimer’s Disease (AD), and that insulin treatment may promote memory function." (PMID 26161852, 2015). "In fact, recent studies have shown that Klotho might prevent the development of Alzheimer's disease associated with aging by inhibiting insulin/IGF-1 signaling and, consequently, oxidative injury in the brain." (PMID 26599613, 2015). "Insulin resistance and excess insulin resulting as a consequence of obesity may play a role in reducing beta amyloid (Aβ) clearance from the brain, increasing the risk of dementia and Alzheimer disease (AD)." (PMID 27275191, 2015). "Samples of autopsied brains from patients with Alzheimer’s disease have shown a deficiency in insulin signaling, thus further confirming the link between disrupted insulin signaling and the well-established decrease of brain glucose uptake associated with Alzheimer’s disease." (PMID 23875003, 2013). "Beyond that, ABCA1 has been implicated in insulin secretion from pancreatic beta cells, and some single nucleoide polymorphisms (SNPs) of this gene have been demonstrated to associate with dementia (rs2230805) and Alzheimer's disease (rs1800977 and rs2422493)." (PMID 22369239, 2012). "Interestingly, HF is associated with increased risk of Alzheimer's disease (AD), and the high insulin levels often observed in patients with T2DM have also been correlated with greater levels of amyloid-beta protein—an early indicator of AD pathogenesis." (PMID 22701196, 2012). "Although increasing evidence has indicated that brain insulin dysfunction is a risk factor for Alzheimer disease (AD), the underlying mechanisms by which insulin deficiency may impact the development of AD are still obscure." (PMID 21044348, 2010).
Alzheimer disease (continued). "In the early stages of Alzheimer’s disease, deficient energy metabolism and less glucose utilization has been occurring and associated with impaired cognition, which suggested that Alzheimer’s disease is a metabolic disease related to brain insulin/insulin-like growth factor resistance." (PMID 37657053, 2023). "Significantly, Alzheimer’s disease has been proposed as “type III diabetes” not only because of the high risk of dementia associated with type II diabetes but also due to the large amount of evidence on the existence of resistance to insulin in the brain during Alzheimer’s disease." (PMID 37569692, 2023). "It has become increasingly apparent that defective insulin signaling may increase the risk for developing Alzheimer’s disease (AD), influence neurodegeneration through promotion of amyloid formation or by increasing inflammatory responses to intraneuronal β-amyloid." (PMID 35213966, 2022). "Defective brain insulin signalling, as well as related signalling by insulin-like growth factor 1 (IGF-1), is associated with neurological disorders, including Alzheimer’s disease, suggesting that cognitive impairment could be related to a state of brain insulin resistance." (PMID 34573112, 2021). "However, it is known women are at an increased risk for Alzheimer’s disease, which could be linked to alterations in CNS insulin signaling and thus differences in the brain/serum insulin ratios." (PMID 34449653, 2021). "Thus, reduced insulin levels and insulin activity may contribute to a number of pathological processes that characterize Alzheimer's disease (AD) such as synaptic loss, limited dendritic arborisation, and memory impairment." (PMID 27195294, 2016). "Finally, recent studies also suggest that Klotho might prevent the development of Alzheimer's disease (AD) associated with aging, probably by inhibiting insulin/IGF-1 signaling and, consequently, oxidative injury in the brain in a murine model of AD." (PMID 26599613, 2015). "In contrast, natural Ad-36 infection was cross-sectional associated with greater adiposity and better glycemic control in humans; in this study compared longitudinal observations of glycemic control (fasting glucose and insulin) in Ad-36 infected versus uninfected adults." (PMID 24324491, 2013). "More generally, failure to maintain ion homeostasis can lead to aging-related diseases, including channelopathies in cancer, defects in insulin signaling, Alzheimer’s disease, and Parkinson’s disease." (PMID 41528311, 2026). "ApoE4 impairs brain insulin signaling, a feature of Alzheimer's disease that correlates with cognitive decline." (PMID 41706741, 2026). "Background/Objective: Glucagon-like peptide-1 receptor agonists (GLP-1 RAs) exhibit neuroprotective properties in preclinical models of Alzheimer's disease (AD), reducing amyloid accumulation, neuroinflammation, and insulin resistance within the brain." (PMID 41599176, 2026). "Clinical and preclinical evidence highlight the efficacy of intranasal insulin (INI) in treating Alzheimer's disease (AD) and delirium, with studies showing significant improvements in cognitive scores and reduced hospital stays (7.9 vs. 12.9 days; p = 0.014)." (PMID 41898218, 2026). "Studies in animal models have shown that insulin resistance and impaired insulin signaling exacerbate neurodegenerative processes in Alzheimer’s disease by affecting amyloid-beta accumulation and neuronal deficits." (PMID 40597598, 2025). "There is also compelling evidence of intranasal insulin improving memory in older adults affected by Alzheimer disease or mild cognitive impairment." (PMID 40795325, 2025). "antioxidant, anti-inflammatory, and anticancer effects, neuroprotective activity, benefits for Alzheimer’s disease, cardioprotectivity, anti-diabetic activity by improving insulin sensitivity, and liver protection." (PMID 41225818, 2025).
Alzheimer disease (continued). "Previous studies have verified the anti-amyloid potential of SPT, which disrupts the amyloidation of insulin in vitro and in vivo, Alzheimer’s disease-related amyloid beta 42, and biofilm-related bacterial amyloids." (PMID 40871379, 2025). "Alzheimer’s disease remains a complex neurodegenerative disorder with multifactorial origins, including amyloid accumulation, tau pathology, insulin resistance, mitochondrial dysfunction, and chronic inflammation." (PMID 40642529, 2025). "Diseases such as Alzheimer's disease produce changes in central insulin sensitivity, which can occur in part because of changes in IR expression." (PMID 39165238, 2025). "SCFAs are known to reduce intestinal inflammatory activity, and MCFAs contribute to energy supply in insulin-resistant tissues, potentially enhancing brain metabolism and playing a role in Alzheimer’s disease prevention." (PMID 40732921, 2025). "Insulin impacts tau phosphorylation and amyloid-β peptide clearance, which are Alzheimer's disease pathological features." (PMID 40536613, 2025). "In Alzheimer’s disease (AD) and cognitive decline, several groups have reported reduced insulin levels in the brain." (PMID 41444683, 2025). "The effect of insulin on neurodegeneration and the progression of certain neurologic disorders like Alzheimer’s disease (AD) is a new topic of discussion, as a strong link is being proven in the latest studies." (PMID 40725728, 2025). "In a randomized, double-blind, placebo-controlled study of people suffering from amnestic mild cognitive impairment or Alzheimer's Disease (AD), intranasal insulin preserved cognitive function compared to placebo." (PMID 40253245, 2025). "The research of oral medications that enhance insulin resistance or sublingual treatment with insulin to restore brain insulin signaling for the management of Alzheimer's disease (AD) is now being implemented." (PMID 39800464, 2025). "Short-term administration of intranasal insulin improved episodic memory in patients with Mild Cognitive Impairment and Alzheimer’s Disease, and a placebo-controlled phase 2 and 3 trial showed a better cognitive performance in the insulin treatment group." (PMID 39350374, 2024). "Restoring insulin, a peptide hormone produced by pancreatic β cells, levels in the CNS has gathered interest as a potential treatment for Alzheimer's disease." (PMID 39267777, 2024). "In 2005, Dr. Eric Steen published one article, ‘Impaired insulin and insulin-like growth factor expression and signaling mechanisms in Alzheimer’s disease - is this type 3 diabetes?’ in the Journal of Alzheimer’s Disease, which had the most citations." (PMID 38586827, 2024). "Among the 96 KEGG pathways associated with OS were chemical carcinogenesis-ROS, colorectal cancer, Parkinson disease, insulin pathway, cellular senescence, Alzheimer’s disease, and other pathways." (PMID 37641831, 2024). "Through proteomic analysis, differentially regulated proteins encompassing dysregulated KEGG pathways included insulin signaling, Alzheimer’s disease, and nicotinic acetylcholine receptor signaling pathways were observed." (PMID 39539936, 2024). "BAT has been involved in various functions that prevent Alzheimer’s Disease, such as regulating energy metabolism, secreting hormones, improving insulin sensitivity, and increasing glucose utilization." (PMID 39119146, 2024). "Addressing these potential negative effects is crucial for the development of safe and effective intranasal insulin formulations for the treatment of conditions like Alzheimer's disease." (PMID 38441832, 2024). "This approach can rapidly be applied in human studies to advance the clinical evaluation of nose-to-brain insulin as a treatment for Alzheimer's disease." (PMID 39267777, 2024). "Further, in mouse models of Alzheimer’s disease and in clinical patients with mild cognitive impairment or early-stage Alzheimer’s disease, intranasal doses of insulin improve attention, memory, and cognitive function." (PMID 39486624, 2024).
Alzheimer disease (continued). "For example, the potential role of cagrilintide in improving insulin sensitivity, reducing cardiovascular risk markers and regulating energy expenditure may offer therapeutic benefits in brain disorders exacerbated by metabolic impairments, such as Alzheimer’s disease." (PMID 39594988, 2024). "Impaired insulin and insulin-like growth factor expression and signaling mechanisms in Alzheimer’s disease - is this type 3 diabetes?" (PMID 38586827, 2024). "These properties of insulin improve memory in healthy people and those with moderate cognitive impairment or Alzheimer’s disease." (PMID 39329976, 2024). "Alzheimer’s disease (AD) is characterized by impaired insulin/insulin-like growth factor-1 signaling in the hippocampus." (PMID 39337316, 2024). "Common features of Alzheimer’s disease include systemic insulin resistance and defects in insulin signaling in the brain, making T2DM an important risk factor for Alzheimer’s disease." (PMID 38952685, 2024). "Summary of studies on insulin-related biomarkers in Alzheimer’s disease, using various assays in plasma, serum, cerebrospinal fluid, or brain homogenates." (PMID 37611907, 2024). "NEP’s involvement in metabolizing natriuretic peptides, insulin, and enkephalins makes it a promising target for treating cardiovascular and Alzheimer’s diseases." (PMID 39764460, 2024). "The goal of this paper is to discuss the neuroprotective effects of moderate training exercise and insulin treatment against Alzheimer's disease (AD)." (PMID 38987609, 2024). "Streptozotocin (STZ)-induced abnormal brain insulin signaling and oxidative stress play crucial roles in the progression of Alzheimer’s disease (AD)-like pathology." (PMID 38977865, 2024). "Insulin degrading enzyme (IDE) plays a critical role in degrading insulin and beta-forming proteins, implicating its significance as a biomarker in metabolic dysfunction and neurocognitive disorders, including Alzheimer's disease (AD)." (PMID 38812908, 2024). "Insulin directly influences the pathogenesis of Alzheimer’s disease through its interaction with Aβ (amyloid-beta) peptides." (PMID 38105338, 2023). "Glucose uptake from the surrounding environment is impaired in the brains of people with Alzheimer’s disease, since this condition seems to result from brain insulin-resistance." (PMID 36679017, 2023). "One study showed a positive correlation between peripheral insulin resistance in Alzheimer’s disease patients and the deposition of Aβ in frontal and temporal brain regions." (PMID 38105338, 2023). "According to previous reports, BCAA supplementation prolonged mouse lifespan, improved cognitive function in a mouse model of Alzheimer’s disease, reduced mouse body weight, and increased adiponectin secretion and insulin sensitivity." (PMID 38045857, 2023). "Insulin also affects proteostasis, impacting amyloid peptide clearance and tau phosphorylation, both of which are hallmarks of Alzheimer’s disease." (PMID 36942499, 2023). "The keyword co-occurrence analysis revealed other major areas of research with limited consideration of sex differences, which included disease states such as dementia, Alzheimer’s disease, and insulin resistance." (PMID 36933153, 2023). "It has been suggested that brain metabolic dysfunction is the primary driver of Alzheimer’s disease, making impairments in insulin signaling important for neurocognitive outcomes." (PMID 37957712, 2023). "The concept of Alzheimer’s disease (AD) being referred to as “type 3 diabetes” due to its connection with insulin resistance and metabolic dysfunction has gained attention in recent years." (PMID 37759801, 2023). "In other words, age-related brain insulin abnormalities are one of the causes of cognitive decline in MCI (mild cognitive impairment) and AD (Alzheimer’s disease)." (PMID 36834911, 2023).
Alzheimer disease (continued). "Effects of insulin action towards the brain are interesting in the context of discovery, suggesting that DM can promote Alzheimer’s disease (AD) due to mechanisms including the attenuation of intracellular-insulin receptor-dependent signaling within the BBB." (PMID 37373216, 2023). "The most common pathways predicted to be affected by these phytochemicals include Olfactory Transduction, Alzheimer’s disease, Insulin Signaling Pathway, Phosphatidylinositol Signaling System, and Vascular Smooth Muscle Contraction." (PMID 37420280, 2023). "Insulin BBB interactions are impaired in Alzheimer’s disease (AD) and CNS insulin resistance is widely prevalent in AD." (PMID 37076875, 2023). "Ferroptosis, Alzheimer's disease, insulin signaling, mapk signaling pathway, and oxidative stress response were all significantly different between the OSAS and normal groups." (PMID 36937508, 2023). "The pathways with the highest number of occurrences included Olfactory Transduction, Alzheimer’s disease, Insulin Signaling Pathway, Phosphatidylinositol Signaling System, and Vascular Smooth Muscle Contraction, respectively." (PMID 37420280, 2023). "When applied to the four NDs Alzheimer's disease (AD), Huntington's disease, and spinocerebellar ataxia types 1 and 3, we predicted multiple members of the insulin pathway, including PDK1, Akt1, InR, and sgg (GSK‐3β), as common modifiers." (PMID 37984409, 2023). "This study further investigated the relationship between pioglitazone use and the risk of developing Alzheimer's disease (AD) in patients newly diagnosed with T2DM, and examined the potential impact of insulin use on this association." (PMID 37095270, 2023). "Some of these proteins are known to cause a number of degenerative diseases in humans, such as amyloid-beta (Aβ) in Alzheimer’s disease (AD), α-synuclein in Parkinson’s disease (PD), and insulin and its analogues in insulin-derived amyloidosis." (PMID 36835194, 2023). "Prospective therapies with insulin and its sensitizer, for example, in Alzheimer’s disease, have been under investigation in recent years." (PMID 35454152, 2022). "Insulin in combination with ART is an interesting potential treatment option considering it has been shown that intranasal administration of insulin is beneficial to Alzheimer’s disease patients in phase II trials." (PMID 36422314, 2022). "Insulin therapy shows improvement in behavior and memory, especially in patients with Alzheimer's disease." (PMID 36258952, 2022). "In 2013, intranasal insulin was shown to be effective in Phase II clinical trials for Alzheimer’s disease." (PMID 36422314, 2022). "Insulin in mammals is also known to play an important role in cognitive function, and many studies in humans have focused on insulin as a potential treatment for Alzheimer’s disease." (PMID 35558436, 2022). "Additional clinical trials are currently being conducted to elucidate the correlation between administering intranasal insulin and both Alzheimer’s disease and mild cognitive impairment." (PMID 34731414, 2022). "Later, attention will be given to the complex relation of mitochondrial dysfunction, brain insulin resistance, and neurodegenerative disease, especially Alzheimer’s disease (AD)." (PMID 35741464, 2022). "CNS-produced insulin is altered in a pathophysiological context in humans; Alzheimer's disease patients have a dramatically reduced content of brain insulin." (PMID 36244663, 2022). "The rapid inhibitory effect of insulin on the onset of oxidative stress observed in our study seems to explain, at least in part, the neuroprotective action of intranasal insulin in the treatment of Alzheimer’s disease and experimental traumatic brain injury." (PMID 36293449, 2022). "For example, insulin has been investigated at the clinical level (up to Phase 3, after intranasal administration) as a treatment for the cognitive decline in Alzheimer’s disease." (PMID 34731414, 2022).